BCL2 (BCL2 apoptosis regulator)
Diseases named in the same sentence as BCL2 in open-access papers (continued):
Sharing a sentence is not in itself a finding about the gene and the disease.
tumor (continued). "The phenomenon of tumour cell death following USMB and chemotherapy is known to be dependent on the regulation of Bcl-2-associated X protein (Bax) and B-cell lymphoma protein 2 (Bcl-2) protein expression." (PMID 35457210, 2022). "Moreover, by inhibiting the production of Bcl-2 protein, intracellular ROS of the tumor was increased, and the PDT efficiency was improved synergistically." (PMID 35624649, 2022). "However, EGCG-mediated cell death of tumor cells has been correlated with the decline in the expression of Bcl-2." (PMID 35402265, 2022). "Along the line, combining PRC2 inhibitor with senolytic agents, such as navitoclax (BCL2 inhibitor), may provide a way to enhance tumor shrinkage and patient survival." (PMID 35169119, 2022). "It is well known that a decreased Bax/Bcl-2 ratio indicated that apoptosis was inhibited, and MMP9 was an important enzyme that degraded the extracellular matrix (ECM) during tumor metastasis and was highly associated with tumor invasion." (PMID 35991881, 2022). "ATL-1 may promote tumor cell apoptosis and inhibit tumor growth by regulating the expression of related proteins in Bcl-2/Bax signaling pathway." (PMID 36686743, 2022). "Here, via an unbiased genome-wide CRISPR/Cas9 screening, we identified loss of NOXA, a B-cell lymphoma 2 (BCL2) family protein in B-cell malignancies, as a pivotal regulator of resistance to CAR T-cell therapy by impairing apoptosis of tumor cells both in vitro and in vivo." (PMID 35370290, 2022). "For example, the overexpression of Gli1, a key protein in the Hh pathway, is considered as a symbol of Hh pathway activation and is able to activate oncogene target genes such as Cyclin-D1, Myc, Bcl-2, Ang1/2, Snai1, Nanog, and Sox2 to promote carcinogenesis and tumour development." (PMID 36358596, 2022). "Specifically observed in APL cell lines (NB4) p-53 induction and p27KIP1 regulation of tumour development driver genes, Bcl-2 and Bax, can be seen seen where the Bcl-2/Bax complex is translocated to the mitochondria after ATO treatment, causing cell cycle inhibition." (PMID 36145693, 2022). "The immunoreactivity of Bcl-2 was significantly decreased after progestin medication, and tumor cell maturation was also observed in the progestin-responsive group, indicating that Bcl-2 downregulation may be closely related to squamous differentiation of EC." (PMID 36551694, 2022). "Our previous study has shown that flavonoids of C. tinctoria had anti-tumor activity against Eca-109 cells and could promote cell apoptosis by regulating the expression of Bcl-2 and Bax." (PMID 35350758, 2022). "BCL2 is known to maintain mitochondrial membrane integrity and crosstalk with pathways like angiogenesis and MAPK pathway; therefore, when Disarib disrupts BCL2, mitochondrial processes and its other crosstalk pathway get affected and contribute towards tumour reduction." (PMID 35885991, 2022). "Consequently, overcoming the resistance of tumor cells to apoptosis by inhibiting the BCL-2 anti-apoptotic protein is a novel therapeutic regimen based on tumor pathogenesis." (PMID 36313628, 2022).
tumor (continued). "Thus, VDT is capable of directly activating the mitochondrial apoptosis pathway even in the presence of Bcl-2 and therefore represents a valuable agent for the treatment of therapy-resistant neoplasia." (PMID 36347842, 2022). "BCL-2 can significantly inhibit tumor apoptosis and is overexpressed in a variety of tumor cells, and silencing BCL-2 expression by siRNA may lead to improved sensitivity of cancer cells to anticancer drugs." (PMID 35953863, 2022). "Moreover, after the drug combination treatment, we found that TXNIP, Bax, and γ-H2AX expressions were upregulated while the bcl-2 and Ki67 expressions were downregulated in the tumor sections of nude mice." (PMID 35414060, 2022). "Immunohistochemical analysis of tumor tissues collected in vivo from subcutaneous tumorigenesis experiment in nude mice showed decreased expression of the Bim protein and increased expression of the Bcl-2 protein in tumor tissues generated by Ishikawa cells with overexpressed SNORD89." (PMID 35790714, 2022). "Remarkably, the combined administration of DOX and ABT199, simultaneously released from the nanofibers, not only prolonged the chemotherapy by DOX but also overcame the drug resistance via inhibiting the Bcl-2 activation and thereby enhancing the apoptosis of tumor cells by ABT199." (PMID 36297356, 2022). "At the same time, pronounced proliferative activity (nuclear Kі-67 expression in 78.4±4.6% of tumor cells), mutant р53 expression (nuclear expression in 92% of cases), and hyperproduction of anti-apoptotic Bcl-2 protein (cytoplasmic expression) were observed in all cases." (PMID 34636027, 2022). "Specifically, the protein expression of the proapoptotic proteins (Bax, Cyt-C, and cleaved caspase-3) was upregulated, and the antiapoptotic protein (Bcl-2) was downregulated, indicating that cisplatin could promote the tumor cell apoptosis." (PMID 35281608, 2022). "Besides the neoplastic cells, some cells of the immune infiltrate of the tumor microenvironment were Kі-67- and Bcl-2-positive." (PMID 34636027, 2022). "To investigate whether the expression of AGK could be a biomarker for predicting the response to venetoclax in DLBCL patients, we performed H&E and BCL-2 immunohistochemical staining for human DLBCL primary tumor tissues of 33 individual patients." (PMID 35910796, 2022). "In addition, it was also found to inhibit the formation of tumor tissue in HepG2 tumor-bearing nude mice by suppressing NF-κB and its downstream Bax/Bcl-2 and Caspase-3." (PMID 36285158, 2022). "Indeed, many tumours upregulate antiapoptotic proteins, such as Bcl-2, Bcl-xL, and Mcl-1, and downregulate oncosuppressive ones, such as Bax." (PMID 35631543, 2022). "MiR-7 and miR-184 directly target Bcl-2, c-my, and Bcl-2, leading to tumor suppression." (PMID 36464702, 2022). "According to a previous study, G0S2 interacts with Bcl-2 and promotes apoptosis in tumor cells." (PMID 35769488, 2022). "By understanding and developing new in vitro tools to regulate the expression of the Bcl-2 proteins in stressed cells, we could potentially augment their function to stimulate the apoptotic response in tumor cells." (PMID 35207544, 2022). "Quantification of apoptosis-related proteins Bax, bcl-2, and proliferation-related protein Ki67 in xenograft tumor sections showed that TXNIP upregulation could promote the apoptosis of DOX-induced drug-resistant cells and inhibit their proliferation in vivo." (PMID 35414060, 2022). "Moreover, the apoptotic activator, Bax, was up-regulated, while the expression of apoptotic inhibitor, Bcl-2, was inhibited in the tumor tissue of the shWDR72 group." (PMID 36385964, 2022). "Tumor-derived exosomes regulated the expression of Bax and Bcl-2 proteins in PANC-1 via miR-3960." (PMID 36284637, 2022). "Additionally, in the BH treatment group, the expression of FOXO3a increased in the tumor tissues, whereas Notch3, β-catenin, and Bcl-2 protein levels decreased." (PMID 35463301, 2022).
tumor (continued). "Heparin binding factor midkine (MK) is also highly expressed in a variety of malignant tumors and treatment with Mk-ASO inhibits the proliferation of tumor cells, reduced the expression of anti-apoptotic proteins survivin and Bcl-2, and promoted apoptosis in tumor cells." (PMID 36569303, 2022). "In the present study, based on the pyroptosis-related expression pattern, we screened for potential small inhibitors that may influence pyroptosis, remodeled the tumor immune microenvironment, and identified Bcl-2 or ATPase inhibitors as potential candidates." (PMID 35990696, 2022). "Tumor cell apoptosis was promoted by down-regulating phosphoinositide 3 kinase (PI3K) and protein kinase B (AKT) signaling pathways, as evidenced by an increased Bcl-2-associated X protein/B cell lymphoma-2 (Bax/Bcl-2) expression ratio." (PMID 36559282, 2022). "In addition, Bcl-2 has a site that can specifically bind to NF-κB, so inhibition of NF-κB activity can also inhibit Bcl-2 expression, which in turn promotes tumor cell apoptosis." (PMID 36104717, 2022). "Results from in vivo experiments showed that compared to unaltered NPs loaded with siRNA (sCS NPs) and naked Cy3-labeled siRNA, sCS NPs-HA directly transported larger quantities of Cy3-labeled siRNA to the tumour locations, inhibiting tumour development by downregulating BCL2." (PMID 36559281, 2022). "FISH assays for MYC/BCL2/BCL6 in tumor tissues were performed in 11 (65%) patients." (PMID 36483984, 2022). "STC2 could regulate drug efflux and drug resistance of tumor cells by regulating the expression levels of P-glycoprotein and Bcl-2 protein." (PMID 35937984, 2022). "Moreover, it was observed that psoralidin upregulated Bax, downregulated Bcl-2, and triggered autophagy, apoptosis, and cell cycle arrest in the HepG2 cells, which leads to the suppression of tumor growth." (PMID 36296934, 2022). "The study underlined that LINC02418 acted as a tumor driver by negatively regulating cell apoptosis through the miR-34b-5p/Bcl-2 axis, indicating that the LINC02418/miR-34b-5p/Bcl-2 axis was one potential indicator for prognosis prediction and a promising therapeutic target for CRC treatment." (PMID 36457043, 2022). "Hence, these compounds are capable of inhibiting tumor angiogenesis, which is also a BCL-2-mediated process." (PMID 36358660, 2022). "Similarly, the total flavonoids of E. ulmoides inhibited tumor growth in H22 tumor-bearing mice through an increase in Bax expression and a decrease in Bcl-2 expression." (PMID 35744822, 2022). "On the other hand, cannabigerol significantly reduces the apoptosis of transformed tumor cells by modulating the levels of Bax and Bcl2 proteins, and may thus enhance the development of tumor processes." (PMID 35887277, 2022). "It has been demonstrated that Bcl-2 suppressed tumor proliferation in vitro in the ACC SW-13 cells." (PMID 35883677, 2022). "Moreover, decreased Bcl‐2 and increased Bax and cleaved caspase‐3 were noted in tumour tissues from mice treated with Erlotinib, and these effects of Erlotinib were abrogated by the injection of HCC827R‐CSC‐EVs (all p < .01)." (PMID 35605028, 2022). "Therefore, the anti-neoplastic efficacy of navitoclax has not been studied at doses likely required to optimally inhibit BCL2 or to determine the potential anti-tumor effect of potent BCL-XL inhibition." (PMID 35659041, 2022). "Additionally, significant decrease in the ratio of Bcl-2/Bax and significant increase in the ratio of cleaved caspase-3/caspase-3 were also detected in GA muscle tissues of C26 tumor-bearing mice compared with health mice." (PMID 35379793, 2022). "Bcl-2 overexpression is observed in various human tumor tissues and cells." (PMID 35655778, 2022).
tumor (continued). "As tumor environment may induce higher stress signal production that is pro-apoptotic in nature, a proportion of cancer cells manage to overexpress BCL-2 and survive the production of this anti-apoptotic signal." (PMID 36142875, 2022). "Lower levels of Bcl-2 may inhibit the growth of tumors, and may also clear senescent tumor cells and promote the development of HCC." (PMID 35308206, 2022). "Furthermore, compared to the vehicle group, the protein expression of Bax and cleaved caspase 3/caspase 3 was significantly increased, while that of Bcl-2 was significantly decreased in the tumor tissues after puerarin treatment." (PMID 35935578, 2022). "In a different study further investigating this same ultrasound-responsive complex, delivery of DOX-loaded PLGA nanoparticles to rabbit tumor models reduced tumor growth, increasing apoptosis of tumor cells via increased Bax expression and decreased Bcl-2 expression." (PMID 36365214, 2022). "On the other hand, the development of non-immune-based treatments will be key for subsets of patients whose tumor cells carry specific abnormalities that could be specifically targeted, such as anti-BCL-2 agents (venetoclax)." (PMID 36225211, 2022). "We previously reported that miR-204 could suppress tumor cell proliferation by down-regulating multiple targets, such as BCL2 and RAB22A." (PMID 36231028, 2022). "However, S1P enhanced the expression of Bcl-2 in macrophages and encouraged the polarization of M2-like macrophages, which further facilitated tumor evasion." (PMID 36518255, 2022). "In both in vitro and in vivo evaluations, our CPT‐bearing chemogene exhibit the targeted co‐delivery of chemo and gene agents to tumor site, efficient BCL‐2 gene knockdown, and strong induced apoptosis of cancer cells, together leading into an enhanced antitumor efficacy." (PMID 37323880, 2022). "In addition, the expression levels of KRAS, XPO1, ERK2 and BCL-2 mRNA were found to be significantly decreased in the residual tumor samples from the combination group." (PMID 35573474, 2022). "Bcl-2 and Bax decrease and increase, respectively, the total amount of cytochrome C released from the mitochondria and these effects dramatically influence the apoptotic process of tumor cells." (PMID 35911648, 2022). "Furthermore, ganetespib significantly increased inhibition of tumor growth mediated by ibrutinib in vivo, confirmed by the changes of the expression levels of Ki-67 and BCL-2 through immunohistochemistry assays." (PMID 35721157, 2022). "Bcl-2 members mostly contain Bcl-2 tumor domains (BH domains), ranging from BH1 to BH4." (PMID 35790714, 2022). "Moreover, the TUNEL staining (green fluorescence), Bax (red fluorescence), Bcl-2 (yellow fluorescence) and Caspase-3 staining (pink fluorescence) of tumor tissue sections all showed that PAE-siRNA induced more apoptosis in most cells." (PMID 35524319, 2022). "On the one hand, cytokines can promote tumor apoptosis through enhancing the expression of apoptosis-related proteins (Bax, Caspase 3 and Caspase8), reduce the expression of apoptosis-inhibiting proteins (Bcl-2, Bcl-xL), and promote tumor apoptosis." (PMID 36304896, 2022). "For this reason, the current study was based on the analysis of the molecular links of c-Myc/HIF-1α gene expression as well as on the expression of other markers such as c-Jun, ERK 1/2, pERK 1/2, VEGF, MMP-9, and Bcl-2, which are involved in Cal-27 survival/proliferation and tumor progression." (PMID 35890188, 2022). "This discovery led our group to investigate miR-15a/16-1’s role in CLL, and in 2005, we demonstrated that miR-15a/16-1 has tumor suppressor functions and can induce apoptosis by targeting the B cell lymphoma 2 (BCL2) gene, a potent inhibitor of the apoptotic program." (PMID 35158777, 2022). "Past research has suggested that Bcl-2 overexpression may also act as a prognostic marker of poor response of PCa tumours to radiotherapy." (PMID 36233505, 2022).
tumor (continued). "Basic research showed that quercetin could trigger BCL2/BAX-mediated apoptosis, necrosis, and mitotic mutation, and inhibit the migration potential of A549 cells, showing good anti-NSCLC tumor activity." (PMID 36523419, 2022). "The co-delivery of both compounds was found to be more effective at treating metastatic breast cancer compared to miRNA-34a or docetaxel alone, where it reduced the expression of Bcl-2, the anti-apoptosis gene, effectively prevented tumor cell migration, and promoted cell apoptosis and cytotoxicity." (PMID 36232799, 2022). "Taken together, these findings support the notion that multiple alterations in apoptotic machinery, mitochondrial structural proteins, or cellular metabolism may represent diverse mechanisms of tumor escape from selective BCL-2 inhibition." (PMID 35185150, 2022). "Similarly, silencing of retinoic acid-inducible gene 1 (RIG1) by using a selective agonist encapsulated in lipid calcium phosphate (LCP) nanoparticles (NPs) enhanced the anti-tumor effect by silencing BCL2, which enhanced apoptosis." (PMID 35154473, 2022). "In a separate study 31 of 51 NPC tumour samples tested, expressed BCL-2." (PMID 35201512, 2022). "In addition, the downregulation of eIF5A increased the expression of Bax, cleaved caspase-3, and cyto C and reduced the expression of Bcl-2 in tumor tissues (i)." (PMID 35874632, 2022). "The BCL-2 relative expression fold has clearly shown that using a single agent of IM or combination therapy decreased the expression, indicating that both treatment strategies have raised the apoptotic effect in tumor cells." (PMID 36078884, 2022). "In addition to pro-angiogenic mediators, STAT3 also upregulates cyclin D1 and Bcl-2, resulting in rapid tumor growth through increased cell-cycle progression and reduced cell death." (PMID 36046049, 2022). "The anti-apoptosis proteins Bcl-2 and Bcl-xl in the Model group were increased compared with those in the control group, especially Bcl-2 which significantly increased, indicating that the tumor cells gained anti-apoptotic ability remarkably." (PMID 35645820, 2022). "At the same time, in vivo studies have found the increased expression of Bcl-2 in PF-treated animal tumor tissues, suggesting that an intrinsic apoptotic pathway may be activated." (PMID 35736152, 2022). "In addition, Western blotting was carried out to detect the protein expression levels of p-p65, c-myc, XIAP, Bcl-2 and cleaved caspase-3 in tumor tissues." (PMID 35541911, 2022). "This study found that cisplatin inhibited the OC tumor formation, increased the expressions of proapoptotic proteins Bax, Cyt-C, and cleaved caspase-3, and downregulated the level of the antiapoptotic protein Bcl-2." (PMID 35281608, 2022). "Additionally, high expression of anti-apoptotic protein BCL2 promotes tumor progression and resistance to cancer treatments." (PMID 35198956, 2022). "Indeed, targeting of MCL-1 has been shown to sensitize cells and effectively inhibit tumor growth in vitro and in vivo when administered in combination with BCL-2/BCL-XL inhibitors." (PMID 35349392, 2022). "Crocin could induce apoptosis in tumor cells by down-regulating the expression of Bcl-2, survivin, cyclin D1, and up-regulating the expression of Bax in BALB/c xenograft tumor." (PMID 34648579, 2021). "Furthermore, when HCC cells were treated with anti-tumor drugs, the Bax level was improved while the Bcl-2 level was limited." (PMID 34793477, 2021).